GPR158 (G protein-coupled receptor 158)
Description:
Metabotropic receptor for glycine that controls synapse formation and function in the brain. Acts as an atypical G protein-coupled receptor that recruits and regulates the RGS7-GNB5 complex instead of activating G proteins. In absence of glycine ligand, promotes the GTPase activator activity of RGS7, increasing the GTPase activity of G protein alpha subunits, thereby driving them into their inactive GDP-bound form. Glycine-binding changes the conformation of the intracellular surface, inhibiting the GTPase activator activity of the RGS7-GNB5 complex, promoting G protein alpha subunits into their active GTP-bound form and regulating cAMP levels. Also able to bind taurine, a compound closely related to glycine, but with a two-fold lower affinity. Glycine receptor-dependent regulation of cAMP controls key ion channels, kinases and neurotrophic factors involved in neuronal excitability and synaptic transmission. Plays a pivotal role in regulating mood and cognition via its ability to regulate neuronal excitability in L2/L3 pyramidal neurons of the prefrontal cortex (By similarity). Also involved in spatial learning by regulating hippocampal CA1 neuronal excitability (By similarity). Acts as a synaptic organizer in the hippocampus, required for proper mossy fiber-CA3 neurocircuitry establishment, structure and function: induces presynaptic differentiation in contacting axons via its interaction with GPC4 (By similarity). In addition to glycine, may also act as a receptor for osteocalcin (BGLAP) hormone: osteocalcin-binding initiates a signaling response that prevents neuronal apoptosis in the hippocampus and regulates the synthesis of neurotransmitters (By similarity).
Synonyms: mGlyR; KIAA1136
Tractability: Small molecule: a structure with a bound ligand is known. Antibody: UniProt places it where antibodies can reach, with high confidence; its Gene Ontology location is reachable by antibodies, with high confidence; UniProt predicts a signal peptide or a membrane-spanning region. PROTAC: UniProt records ubiquitination sites on it; ubiquitination databases record sites on it.
Target class: Family C G protein-coupled receptor; Membrane receptor
Gene: Protein-coding gene on chromosome 10 (25,174,802 to 25,602,229, forward strand). Ensembl gene ENSG00000151025.
Subcellular location: Cell membrane; Postsynaptic cell membrane; Presynaptic cell membrane; Nucleus
Gene Ontology:
Molecular function: enzyme activator activity; G protein-coupled glycine receptor activity; transmembrane signaling receptor activity; G protein-coupled receptor activity
Biological process: G protein-coupled receptor signaling pathway; protein localization to plasma membrane; regulation of G protein-coupled receptor signaling pathway; brain development; cognition; positive regulation of neurotransmitter secretion; regulation of synapse organization
Cellular component: nucleus; plasma membrane; postsynaptic membrane; presynaptic membrane; membrane; postsynaptic density membrane
Genetic constraint (gnomAD): Loss-of-function variants: 24 observed, 49.71 expected, observed/expected ratio (o/e) 0.48, 90% interval 0.35 to 0.68. The upper end of that interval is the gene's LOEUF score, 0.68, which puts it in group 2 of 6, group 1 being the genes least tolerant of losing a copy. Missense variants: 1,192 observed, 1,273 expected, observed/expected ratio (o/e) 0.94, 90% interval 0.89 to 0.98. Synonymous variants: 476 observed, 508.8 expected, observed/expected ratio (o/e) 0.94, 90% interval 0.87 to 1.01.
Homologues: Orthologues: chimpanzee GPR158 (99% identical), macaque GPR158 (97% identical), pig GPR158 (89% identical), dog GPR158 (89% identical), rat Gpr158 (87% identical), mouse Gpr158 (86% identical), guinea pig GPR158 (85% identical), rabbit GPR158 (78% identical), tropical clawed frog gpr158 (56% identical), zebrafish gpr158a (53% identical), zebrafish gpr158b (51% identical). Paralogues in human: GPR179 (37% identical).
Diseases named in the same sentence as GPR158 in open-access papers:
GPR158 is named in the same sentence as 55 diseases in open-access papers, as found by Europe PMC text mining. Sharing a sentence is not in itself a finding about the gene and the disease. The quoted sentences say what the papers report.
depression (16 papers, 2018 to 2026). "GPR158 is highly expressed in brain regions implicated in the regulation of depression-related behaviors, such as the hippocampus, prefrontal cortex and nucleus accumbens (NAc)." (PMID 38884814, 2024). "Conversely, GPR158 is associated with depression after chronic stress, and is downregulated in the sodium valerate supplemented group (log2Fold change: −0.26; unadjusted p < 0.01)." (PMID 37961441, 2023). "There are some orphan GPCRs which are highly expressed in the PFC and that have been associated with anxiety- and depression-like traits, such as GPR158, GPR56, GPR3, and GPR26." (PMID 33589739, 2022). "GPR158 has been demonstrated to be implicated in the etiology of affective disorders, for instance, memory loss, cognitive diseases and depression, mainly attributed to the fact that GPR158 plays a critical role in the structural organization and functional formation of the synapse." (PMID 35456013, 2022). "Several lines of evidence obtained in this study suggest that orphan receptor GPR158 may be one of the key molecular factors determining an individual’s susceptibility or resiliency to stress-induced depression." (PMID 29419376, 2018). "In humans, GPR158 mRNA is up‐regulated in the PFC of individuals with major depressive disorder, which is conserved in rodent models of stress‐induced depressive behaviour and can be rescued through genetic manipulation of GPR158." (PMID 38073127, 2024). "The interaction of GPR158 with RGS7 in the PFC of mice is a key mechanism leading to behavioral abnormalities in stress-induced depression." (PMID 36979415, 2023). "GPR158 is a novel regulator of stress-responsive behaviors and is highly upregulated in people with major depression disorder." (PMID 37961441, 2023). "To date, studies on GPR158 have focused on Alzheimer’s disease (AD), depression, tumors, and ocular hypertension." (PMID 36979415, 2023). "GC increased the expression of GPR158 at the transcriptional and translational level, which suggests a role of the glucocorticoids–GPR158 axis in anxiety and depression." (PMID 35456013, 2022). "GPR158 gained attention through its remarkable upregulation in PFC in a stress-induced depression animal model but also in human patients diagnosed with MDD." (PMID 33589739, 2022). "In summary, our data demonstrates that GPR158 plays a prominent role in the regulation of stress-induced depression via adaptations in synaptic plasticity." (PMID 29419376, 2018). "Together, these results indicate the involvement of GPR158 in the control of stress-induced depression." (PMID 29419376, 2018). "Here, we identified the orphan receptor GPR158 as a novel regulator operating in the prefrontal cortex (PFC) that links chronic stress to depression." (PMID 29419376, 2018). "OCN appears to regulate the expression of these receptors, suggesting that its positive effects on depression‐like behaviors may be mediated by GPR158 and GPR37, implying that these receptors could be involved in the regulation of OCN on emotion." (PMID 40746130, 2025). "Given the link between stress, depression and alcohol use, GPR158 may also be effective for the treatment of alcohol and substance use disorders." (PMID 38073127, 2024). "Interestingly, GPR158 has also been identified as a key mediator of stress-induced depression both in mouse models and in humans." (PMID 38884814, 2024). "Moreover, in multiple behavioral paradigms including the sucrose preference test for anhedonia, GPR158 KO mice showed resilience to chronic stress-induced depression." (PMID 38884814, 2024). "Multiple experimental findings suggest that GPR158 may play key functional roles in Alzheimer’s disease (AD), depression, tumor formation, and intraocular pressure." (PMID 36979415, 2023).
depression (continued). "Among orphan GPCRs, GPR158 is of particular interest as a novel GPCR, as it has been shown to play a critical role in the etiology of cancers and mental illnesses, e.g., prostate cancer, glioma and depression, though the properties of GPR158 are yet to be fully elucidated." (PMID 35456013, 2022). "GPR158 plays a part in mediating chronic stress-induced depression." (PMID 35456013, 2022). "For instance, glucocorticoid disorders could lead to depression via the modulation of GPR158 levels." (PMID 36467406, 2022). "Under chronic stress conditions, GPR158 responds to glucocorticoids and induces depression." (PMID 36467406, 2022). "GPR158 is highly upregulated in the PFC of human subjects with major depressive disorder." (PMID 29419376, 2018). "To further explore the role of GPR158 in stress-induced depression we utilized the UCMS model." (PMID 29419376, 2018). "We identify the orphan receptor GPR158 as a key modulator of stress-induced depression." (PMID 29419376, 2018). "At this time, it is unknown if osteocalcin is involved in mediating the effects of GPR158 in stress-induced depression and further investigation is warranted." (PMID 29419376, 2018). "Thus, GPR158 may function at the critical nexus of stress, depression, and synaptic plasticity linking these processes at the molecular level." (PMID 29419376, 2018). "In our study, we found that the expression levels of GPR158 and GPR37 were significantly changed in CUMS mice with depression‐like behaviors." (PMID 40746130, 2025). "Although the involvement of other regions in mediating the actions of GPR158 on depression-like and stress related behaviors cannot be ruled out, its effects in PFC appear to be sufficient for driving behavioral changes supported by both gain and loss of function experiments." (PMID 29419376, 2018). "Western blot analysis revealed a significant elevation in GPR158 protein levels in the dlPFC of MDD patients compared to match controls, suggesting that this receptor may be involved in the neuropathology of depression." (PMID 29419376, 2018).
prostate carcinoma (9 papers, 2015 to 2025). A carcinoma that arises from epithelial cells of the prostate gland. "GPR158 expression is associated with a neuroendocrine cell phenotype present in scattered foci of prostate cancer." (PMID 36467406, 2022). "Specifically, the expression and upregulation of GPR158 has been linked to tumour progression and unfavourable survival in prostate cancer and gliomas, but the literature is otherwise limited with regard to targeted GPR158 therapy." (PMID 34830751, 2021). "The expression of GPR158 is significantly upregulated in prostate cancer, neuroendocrine tumors of the digestive tract, mucinous ovarian cancer, and various other malignancies." (PMID 40337551, 2025). "As mentioned, GPR158 expression was stimulated by androgens and promotes prostate cancer (PC) cell proliferation significantly." (PMID 35456013, 2022). "GPR158 is a newly characterized cell surface protein that plays the same role, as other G-protein coupled receptors (GPCRs), on promoting prostate cancer (PCa) malignancy." (PMID 35296245, 2022). "Our results are discrepant to those of a study on prostate cancer where increased expression of GPR158 correlates with poorer survival." (PMID 29720725, 2018). "Moreover, the up-regulation of GPR158 in prostate cancer (PCa) and ovarian carcinoma indirectly affects the endocrine system." (PMID 36467406, 2022). "GPR158 has previously been shown to be involved in prostate cancer growth and progression, wherein up-regulation of GPR158 in Pten homozygous knock-out mice could contribute to tumor invasion." (PMID 31533654, 2019). "Notably, transient transfection of GPR158 promotes proliferation in prostate cancer cells." (PMID 40337551, 2025). "This could be related to the specific pathobiology of prostate cancer, where enrichment of GPR158 expressing neuroendocrine cells (thought to represent transdifferentiated prostate epithelial cells) show more aggressive clinical behaviour and thus are associated with poorer survival." (PMID 29720725, 2018). "A further difference between prostate cancer and brain tumours is that in the former, the C-terminal portion of GPR158 is translocated to the nucleus whilst we did not observe nuclear staining in CNS grey matter or in glioma cells using a specific anti-GPR158 C-terminal antibody." (PMID 29720725, 2018).
Anxiety (6 papers, 2019 to 2024). Intense feelings of nervousness, tension, or panic often arise in response to interpersonal stresses. "For Gpr158 KO, a robust anxiety phenotype was detected previously." (PMID 31749686, 2019). "To assess the cellular localization, expression, and function of GPR158, we generated an epitope-tagged GPR158 mouse model (GPR158Tag) that exhibited normal motor, cognitive, and social behavior, no deficiencies in social memory, and no anxiety-like behavior compared to C57BL/6J control mice at P60." (PMID 36979415, 2023). "Taken together, in the absence of motor and visual deficits or overt anxiety-like behavior, Gpr158 KO mice exhibited spatial memory deficits in the MWM paradigm." (PMID 31749686, 2019). "Taken together, whereas Gpr158 KO mice show no deficits in aversive memory acquisition, they do exhibit spatial memory deficits and difficulty in acquiring extinction memory, in the absence of motor and visual impairments or anxiety." (PMID 31749686, 2019).
glioma (6 papers, 2018 to 2023). A benign or malignant brain and spinal cord tumor that arises from glial cells (astrocytes, oligodendrocytes, ependymal cells). "In human gliomas, high levels of miR-449a and low expression of GPR158 are associated with higher malignancy and poorer survival." (PMID 29720725, 2018). "In conclusion, we show here that GPR158 RNA and protein expression correlate with distinct diagnostic glioma entities, suggesting that GPR could represent a biomarker for stratifying these tumours." (PMID 29720725, 2018). "High miR-449a expression levels correlate with shorter survival, whilst high GPR158 expression is associated experimentally with neural phenotypes, cell differentiation and clinically with lower glioma grades and better patient survival and may serve as predictive biomarker." (PMID 29720725, 2018). "GPR158 can regulate the malignant phenotype of glioma, and, as a biomarker, quantitatively characterize the malignant process of glioma independent from the miR-449a target CCND1 (the expression of CCND1 remains largely independent of the tumor subtype)." (PMID 35456013, 2022). "We show that miR-449 directly targets and downregulates CCND1, resulting in reduced proliferation in vitro, and GPR158, antagonising neural differentiation and apoptosis in glioma stem cells." (PMID 29720725, 2018). "In contrast, expression of GPR158 and (pro-) neural markers is high in low-grade gliomas and typically much lower in GBM." (PMID 29720725, 2018). "The correlation of GPR158 expression with molecular subtypes, patient survival and therapy response suggests a possible role of GPR158 as prognostic biomarker in human gliomas." (PMID 29720725, 2018). "Using these criteria and TCGA RNA sequencing data, we investigated GPR158 expression in these glioma subtypes." (PMID 29720725, 2018). "The correlation of GPR158 expression with molecular subtypes, patient survival and therapy response suggest a possible role for GPR158 as a prognostic biomarker and a therapeutic target in human gliomas." (PMID 35456013, 2022). "Remarkably, GPR158 may switch the glioma phenotypic plasticity via the downregulation of proliferation, migration and glioma stem-like cell formation, and via the induction of proneural differentiation and apoptosis simultaneously." (PMID 35456013, 2022). "GPR158 has higher methylation level in esophageal squamous cell carcinoma compared with mucosa, which can induce apoptosis and is related to the high survival rate of glioma patients." (PMID 35463319, 2022). "In summary, in both the NHNN and the TCGA glioma cohorts, we confirmed that higher GPR158 transcript and protein expression levels correlate with better survival, and patients with GPR158high IDHwt GBM responded significantly better to chemotherapy compared to patients with GPR158low tumours." (PMID 29720725, 2018). "mRNA expression data of miR-449a and GPR158 were confirmed on 25 frozen glioma samples and 5 CNS samples from our own collection (miR-449a: CNS, n = 5; O, n = 7; A, n = 7; GBM, n = 8; and GPR158 CNS, n = 5; O, n = 8; A/GBM-IDH, n = 8; GBM, n = 9) by RT-qPCR analysis." (PMID 29720725, 2018). "Moreover, GPR158 has been shown to promote glioma stem cell differentiation and apoptosis." (PMID 31533654, 2019). "GPR158 promotes glioma stem cell differentiation and induces apoptosis and is highest expressed in the cerebral cortex and in oligodendrogliomas, lower in IDH mutant astrocytomas and lowest in the most malignant form of glioma, IDH wild-type glioblastoma." (PMID 29720725, 2018).
Alzheimer disease (4 papers, 2022 to 2025). A progressive, neurodegenerative disease characterized by loss of function and death of nerve cells in several areas of the brain leading to loss of cognitive function such as memory and language. "Although the precise biological mechanisms underlying the OCN/GPR158 signaling pathway remain incompletely understood, its association with neurodegenerative diseases (NDs), including Alzheimer’s disease (AD) and Parkinson’s disease (PD), is becoming increasingly evident." (PMID 40337551, 2025). "Of importance, GPR158 appears to be correlated with ageing and cardiac diseases caused by aFGF (acidic fibroblast growth factor)-induced collagen deposition and associated with the atrophy pattern and Alzheimer’s Disease, which may be indicative for GPR158 in age-onset diseases." (PMID 35456013, 2022).